MBP (myelin basic protein)
Diseases named in the same sentence as MBP in open-access papers (continued):
Sharing a sentence is not in itself a finding about the gene and the disease.
tumor (continued). "Specifically, in the case of oral administration of MBP-11901, we noticed that the time required for the tumor to disappear was similar regardless of the administration interval." (PMID 35454900, 2022). "Compared with HepG2 or Hep3B, administration of MBP-11901 to the Huh-7 subcutaneously implanted model did not result in tumor disappearance, although the tumor weight was significantly reduced." (PMID 35454900, 2022). "Preparations isolated from the CC had a strong increase in the proportion of cells positive for SOX10, the majority of which also expressed O4, but not MBP, confirming that transcriptomic signatures reflect changes in tumour cell fate." (PMID 33846316, 2021). "Non-tumor components included endothelial cells (expressing VWF, CDH5, ECSCR, SLCO2A1, and MYCT1), pericytes (marked by RGS5, MCAM, and PDGFRB), normal oligodendrocytes (showing PTGDS, MBP, TF, and MOG expression), and TAMs (identified by CD14, AIF1, FCER1G, FCGR3A, TYROBP, and CSF1R)." (PMID 41394801, 2025). "It was revealed on immunohistochemistry that the tumor showed positive immunoreactivity for vimentin, α-smooth muscle actin (α-SMA), and CD68, but was negative for anaplastic lymphoma kinase (ALK), S-100, CD34, CD117, kinesin-like protein-1 (KP-1), myelin basic protein (MBP), and desmin." (PMID 25022487, 2014). "SOX10+ tumour cells were significantly less proliferative than tumour cells that remained SOX10- within the same region and occasionally expressed the immature oligodendrocyte markers CNP and CC1, but were again negative for the mature marker MBP." (PMID 33846316, 2021).
infection (29 papers, 2011 to 2025). The state of being infected such as from the introduction of a foreign agent such as serum, vaccine, antigenic substance or organism. "In humans, we identified the presence of autoreactive IgG antibodies in the cerebrospinal fluid (CSF) of second stage HAT patients that recognised human brain lysates and MBP, consistent with our findings in experimental infections." (PMID 37983289, 2023). "While total GFAP+ astrocyte numbers were stable, IL-33+ mature-myelinating oligodendrocyte cell numbers (MBP+IL-33+) and overall MBP staining were decreased post-infection." (PMID 37983247, 2023). "Housing effect on antibody titers before infection At 38 days of age, MBP-IgM titers were affected by housing (F(1.54) = 10.0, P < 0.01), with higher titers in barren compared to enriched housed pigs." (PMID 29126442, 2017). "Effects of infection with PRRSV on the titers on day 44 up till day 52 were found for IgM binding MBP and PC-BSA." (PMID 29126442, 2017). "In cells induced to differentiate 12 hours after DISC1-GFP-Adv infection, expression of the myelin genes, CNPase and MBP, were decreased at both the mRNA and protein level, compared with control (GFP-Adv) infected cells." (PMID 24516667, 2014). "We also identified MBP, a highly abundant CNS protein, to be one of the host antigens recognised by these infection-induced IgG autoantibodies in both mice and humans during chronic infections, potentially explaining the local antibody deposition observed in the brain in our histological analyses." (PMID 37983289, 2023). "Moreover, the ingenuity pathway analysis revealed protein molecules such as VLDLR, MBP and APP that are associated with altered profile of cholesterol, fatty acids and triglycerides with infection-related CNS disorders." (PMID 37876925, 2023). "Furthermore, using a targeted screening approach we identified myelin basic protein (MBP) as one of the host antigens detected by autoreactive IgG antibodies in mouse serum and human CSF collected during the chronic stage of the infection." (PMID 37983289, 2023). "In this study, BLL and infection history varied between seasons in MBP and TBP." (PMID 37508115, 2023). "Thus, barren housed pigs with a relatively higher increase in MBP-IgM following infection, showed a faster reduction of viral RNA in serum." (PMID 29126442, 2017). "However, in the current study, NA(A)b, particularly of the IgM isotype, binding all three antigens were affected by housing conditions, and, moreover infection with PRRSV affected MBP-IgM NA(A)b in a housing-dependent manner." (PMID 29126442, 2017). "Thus, enriched infected pigs showed a higher and more prolonged increase from infection onwards in MBP-IgM." (PMID 29126442, 2017). "Only in infected enriched pigs, MBP-IgM titers continued to increase from day 4 to day 8 after infection (day 48–52 of age), and infected pigs from enriched housing showed a higher increase in titers starting directly after PRRSV until 8 days after infection than controls and barren infected pigs." (PMID 29126442, 2017). "For example, in previous works, we obtained antibodies to the myelin basic protein from the blood plasma of MS, SLE, and HIV-infection anti-histone antibodies of MS, and HIV-infected patients." (PMID 36430159, 2022). "Similar to our previous study, staining for myelin basic protein (MBP) showed apparent demyelination, especially at 21 days post-infection (dpi)." (PMID 35296090, 2022). "In this study, we investigated the effect of environmental enrichment versus barren housing on the level of NA(A)b binding KLH, MBP, and PC-BSA prior to transport and relocation, after transport and after infection with PRRSV and A. pleuropneumoniae." (PMID 29126442, 2017). "Housing significantly affected the overall serum levels of NA(A)b binding KLH, MBP and PC-BSA, and before infection barren housed pigs had significantly higher levels of NA(A)b than enriched housed pigs, except for KLH-IgM and PC-BSA-IgG." (PMID 29126442, 2017).
infection (continued). "On the other hand, in the MBP, there was no seasonal difference in Pb concentration or infection history." (PMID 37508115, 2023). "Although we could not detect the His6-tagged SfAV Fanzor protein, we observed robust expression of the MBP/GFP-tagged SfAV Fanzor protein in vivo, with the larvae turning completely green five days post infection." (PMID 37971304, 2023). "M. leprae was shown to infect and persist in SC and subsequent infection promoted dedifferentiation of host SC into progenitor stem-like cells with a marked downregulation of myelin genes (MPZ, MBP, and Erg2) and a reduced remyelination capacity in infected SC." (PMID 36611893, 2022). "The results of the Western blot analysis showed that rTsGSCP was recognized by anti-rTsGSCP serum and infection serum but not by anti-MBP-tag serum and preimmune serum." (PMID 34446106, 2021). "Although FedF on its own is not immunogenic when given orally, FedF-conjugates with MBP or F4-fimbriae did provide some protection against infection." (PMID 34721427, 2021). "Moreover, changes in MBP-IgM and PC-BSA-IgM following infection were different for enriched and barren housed pigs." (PMID 29126442, 2017). "After infection with A. pleuropneumoniae, there was no infection effect on MBP-IgM deltas (delta 53–52, 54–52), but only of the interaction between housing and delta-day (F(1.50) = 9.9, P < 0.01), with a lower decrease in titers from delta 54–52 than from delta 53–52 in barren pigs only." (PMID 29126442, 2017). "However, LPS-treatment of animals that recovered from ACA infection led to the appearance of MBP 89–101-reactive T cells but not EAE." (PMID 24879066, 2014). "It has been proposed that exposure to or infection by several viruses, such as hepatitis B and EBV, activates T lymphocytes that recognize viral proteins with structural similarities to CNS proteins, including myelin basic protein (MBP); this concept is known as the “molecular mimicry hypothesis”." (PMID 41341415, 2025). "By day 6 of post-infection, GFAP staining was absent in the inferior medial REZ, despite intact myelin indicated by myelin basic protein (MBP) staining." (PMID 39727657, 2024). "Myelin Basic Protein (MBP) staining surrounded the SARS-CoV-2_S without colocalization, suggesting that the cells positive for the infection could also be myelinated neurons and not oligodendrocytes." (PMID 34608167, 2021).
neurodegenerative disease (23 papers, 2011 to 2025). A disorder of the central nervous system characterized by gradual and progressive loss of neural tissue and neurologic function. "MBP is essential for the formation and maintenance of myelin in the CNS, and demyelination and loss of oligodendrocytes are found in neurodegenerative diseases like Alzheimer disease." (PMID 31209203, 2019). "This suggests that MBP dysregulation may contribute to cytoskeletal instability, which is a hallmark of neurodegenerative diseases." (PMID 40783910, 2025). "MBP is a prime example of an apparently simple, but in fact biochemically and structurally complex molecule, which is closely linked to both normal nervous system development and neurodegenerative disease." (PMID 34889995, 2022). "Since MOG and MBP fulfill the three criteria outlined in Section “The cause of the cause of degenerative diseases,” these two proteins are candidate pSAgs involved in the autoimmune inflammatory/demyelination of cholinergic neurons in the CNS white matter MS patients." (PMID 28421005, 2017). "As oligodendrocyte loss and myelin dysfunction has recently been emphasized in neurodegenerative diseases, including ALS, it is essential to investigate the relationship between SVAs and MBP differential expressions." (PMID 38540776, 2024). "Mature oligodendrocytes express myelin basic protein (Mbp) and proteolipid protein 1 (Plp1) and are critical for the myelination of axons and involved in neurodegenerative diseases in brain." (PMID 35399523, 2022). "Patients with Lewy body–associated dementia, a neurodegenerative disease, have high levels of autoantibodies against, for example, myelin oligodendrocyte glycoprotein (MOG) and myelin basic protein (MBP)." (PMID 23946635, 2013). "The presence of MBP in serum or the CSF is an indication of myelin damage in general, and testing for it may be applicable to diagnosis of different neurodegenerative disease states, including spinal cord demyelination." (PMID 34889995, 2022). "In addition to anti-MBP antibodies, the MBP protein per se has been studied and used as a possible biomarker for brain tissue injury and neurodegenerative disease, both in serum and in the CSF." (PMID 34889995, 2022). "To investigate the effects of MBP on neurons, we used primary hippocampal neurons because of their physiological importance and the fact that there is extensive demyelination in the hippocampus during injury and neurodegenerative disease." (PMID 25255088, 2014). "Interestingly, when we co-stain for AT8, a marker commonly used to study hyperphosphorylated tau in neurodegenerative disease, we reveal that these areas of axon and myelin loss (i.e. NF200- and MBP- signal) correspond with abnormally high levels of AT8+ phosphorylated tau." (PMID 37531953, 2023). "Therefore, as a molecular link between the nervous and immune systems, Golli-MBP may bridge those systems and contribute to neuroimmune driven neurodegenerative diseases." (PMID 25964736, 2015). "We observed a significant reduction in myelination-related genes (e.g., MBP, MOG, PLP1), hence confirming the pathological feature of neurodegenerative diseases." (PMID 39622637, 2025).
cancer (22 papers, 1976 to 2025). A tumor composed of atypical neoplastic, often pleomorphic cells that invade other tissues. "We have also shown that MBP loci contain genes attributable to specific pathways, some of which predispose to other traits such as longevity and cancer." (PMID 29146897, 2017). "MBP has been shown to induce cellular proliferation, inhibit apoptosis, and found to be associated with advanced stages of cancer and poor prognosis." (PMID 23646114, 2013). "We also observed a positive significant (p < 0.05) correlation between the ESR1 gene expression level and NLGN4X expression in BRCA-Her2 and BRCA-LumB cancer patients and MBP expression in BRCA-LumA and -LumB patients." (PMID 38137332, 2023). "Studies have shown that MBP plays a role in immunity: it was serially measured in 177 CSF samples from 33 patients with leptomeningeal metastases and compared to 34 cancer controls to determine the degree of autosensitization to MBP." (PMID 38137332, 2023). "We confirmed the HCC-specific efficacy of MBP-11901 through in vitro screening using various human cancer cell lines, and verified its effectiveness in various HCC cell lines." (PMID 35454900, 2022). "Thus, early detection of actin could serve as a biomarker to predict the emergence of tobacco related disorders (cancers, heart diseases), while MBP abnormalities and low BDNF levels might serve as early biomarkers for FASD." (PMID 40061215, 2025). "On the other hand, the ESR1 and MBP correlation was positive in BRCA-LumA and Lum-B cancer patients." (PMID 38137332, 2023). "Co-culture of Schwann cell with HSC-3 cancer cells also resulted in Schwann cell activation as confirmed by the overexpression of c-Jun, GFAP, p75NTR, and downregulation of MBP." (PMID 33469141, 2021). "It has been reported that lymphocytes from cancer patients give positive responses to PPD, myelin basic protein, tumour basic protein, and certain histone fractions in the MEM test." (PMID 60119, 1976). "Furthermore, the putative novel miRNA EGCG-MDAMB231-5 targets MBP (Myelin Basic Protein), HIC1 (hypermethylated in cancer 1), and P3H2 (Prolyl 3-Hydroxylase 2), SLC6A2 (Solute Carrier Family 6 Member 2) genes." (PMID 36276982, 2022). "Mice without cancer and receiving combination ICI, cancer-bearing mice with or without ICI treatment showed a significant decline in the myelin basic protein immunoreactivity." (PMID 40313772, 2025). "Several genes that were highly expressed in Cluster 3 were well known to be preferentially expressed in normal oligodendrocytes, including CLDN11, MBP, PLP1, and KLK6, indicating that these cells are not cancer cells." (PMID 27368803, 2016).
neurological diseases (17 papers, 2005 to 2025). "Both signatures included a number of genes (MBP, MOBP, MAG, OLIG1, and OLIG2) previously found in glial cells, several of which have been linked to neurological diseases." (PMID 16168081, 2005). "Likewise, CSF analyses have demonstrated anti-MBP IgG-secreting cells in MS patients but also—albeit at lower frequencies—in other neurological disorders (OND)." (PMID 41226806, 2025). "However, its combination with other biomarkers, such as glial fibrillary acid protein GFAP, Myelin basic protein (MBP), and interleukins, could provide disease-specific signatures to discriminate between neurological disorders in the future—a currently unmet need in the real-world clinical setting." (PMID 40309835, 2025). "The microarchitectural features of Neurologic Disease demonstrated progressive decline in axons (anti-NF200) and myelin (anti-MBP)." (PMID 37258605, 2023). "We evaluated in sera and CSF of patients with MS and with other neurological diseases (OND) the humoral response against EBV/MAP peptides and the IRF5/MBP." (PMID 26956729, 2016). "Previous studies, including our own, have demonstrated that IgM and IgA antibodies have been detected against myelin basic protein (MBP), myelin oligodendrocyte glycoprotein (MOG), and other neural antigens in subgroups of patients suffering from MS and other neurologic disorders." (PMID 26290755, 2015).
peripheral neuropathy (4 papers, 2013 to 2025). A disorder affecting the peripheral nervous system. "A recent study established that db/db mice colonized with gut microbiota from patients with diabetic sensorimotor peripheral neuropathy (DSPN) exhibited exacerbated peripheral neuropathy and significantly reduced MBP level compared to the control groups." (PMID 41264657, 2025). "Testing applicability to the peripheral nervous system, we applied rCATS to an FFPE sural nerve biopsy from a patient suspected with peripheral neuropathy and validated locations of axon cylinders and myelin with immunolabelings for neurofilament H and myelin basic protein (MBP), respectively." (PMID 37653226, 2024).
movement disorder (2 papers, 2020 to 2024). Neurological conditions resulting in abnormal voluntary or involuntary movement, which may impact the speed, fluency, quality and ease of movement. "Myelin basic protein (MBP) and the soluble form of TREM2 were quantified in a comprehensive movement disorder cohort from two different neurological centers, comprising a total of 171 CSF samples." (PMID 39666067, 2024). "The present study reports on the quantification of myelin basic protein (MBP) and soluble triggering receptor expressed on myeloid cells 2 (TREM2) in the CSF of a comprehensive movement disorder cohort." (PMID 39666067, 2024).
cardiovascular disease (1 paper, 2021). "Furthermore, exposure to MBP at 25 μg/L (approximately 0.1 μM) has been found to impair cardiovascular function and induce the development of vascular-cardiovascular disease states in zebrafish." (PMID 33922211, 2021).
colonic polyps (1 paper, 2003). "In our previous study, we demonstrated that overexpression of ILK in colonic polyps coincided with an increase in the immunoprecipitated ILK MBP phosphotransferase activity." (PMID 12771992, 2003).
connective tissue diseases (1 paper, 2011). "Furthermore, significant increase of circulating autoantibodies against MBP protein was demonstrated in RA patients as compared to those with other connective tissue diseases, implicating its role as a disease-associated biomaker." (PMID 21673997, 2011). "As a result, the titer of anti-MBP antibody was markedly higher in plasma of RA patients compared to healthy controls (p<0.001) and patients with other connective tissue disorders (p<0.001)." (PMID 21673997, 2011). "The average levels of anti-MBP antibody in plasma of RA patients were much higher than those of healthy controls and patients with seven other connective tissue diseases (p<0.001)." (PMID 21673997, 2011). "Circulating autoantibody against MBP derived from human brain was quantified by ELISA between patients with RA, other connective tissue diseases and healthy controls." (PMID 21673997, 2011). "From these results, we concluded that higher levels of anti-MBP antibody in RA patients than in healthy controls and in patients with other connective tissue diseases was attributed to autoantibodies binding to citrullinated MBP." (PMID 21673997, 2011).
inflammation (1 paper, 2021). Aberrant reaction of the microcirculation characterized by movement of fluid and leukocytes from the blood into extravascular tissues. "In this experimental set up, brain inflammation was induced by systemic transfer of MBP-reactive T-cell lines, but the respective antibodies were directly injected into the cerebrospinal fluid via the cisterna magna." (PMID 33242149, 2021).
metabolic disease (1 paper, 2014). A congenital disorder (due to inherited enzyme abnormality) or acquired (due to failure of a metabolically important organ) disorder resulting from an abnormal metabolic process. "Notably, central genes (APP, MBP, and APOE) in the network are implicated in neuro-pathological disorders and metabolic disease, but have not previously been assigned significance in brain metastasis." (PMID 25593989, 2014).
peripheral nerve diseases (1 paper, 2023). "This suggests that the high myelination efficiency observed in IVMDE could generate new indexes for evaluating myelination allowing discovery of therapeutic interventions that normalize the myelin profile length and MBP intensity as seen in many peripheral nerve diseases causing dysmyelination." (PMID 37224113, 2023).